LRRC52 (leucine rich repeat containing 52)
Description:
Auxiliary protein of the large-conductance, voltage and calcium-activated potassium channel (BK alpha). Modulates gating properties by producing a marked shift in the BK channel's voltage dependence of activation in the hyperpolarizing direction, and in the absence of calcium. KCNU1 channel auxiliary protein. Modulates KCNU1 gating properties.
Synonyms: FLJ25811
Tractability: Antibody: UniProt places it where antibodies can reach, with medium confidence; UniProt predicts a signal peptide or a membrane-spanning region; its Gene Ontology location is reachable by antibodies, with medium confidence.
Gene: Protein-coding gene on chromosome 1 (165,544,000 to 165,563,957, forward strand). Ensembl gene ENSG00000162763.
Subcellular location: Cell membrane
Pathways (Reactome):
Sensory Perception: Sensory processing of sound by inner hair cells of the cochlea
Gene Ontology:
Molecular function: potassium channel activator activity; protein binding; transmembrane transporter binding; voltage-gated potassium channel activity; potassium channel activity
Biological process: positive regulation of voltage-gated potassium channel activity; potassium ion transmembrane transport
Cellular component: voltage-gated potassium channel complex; plasma membrane
Genetic constraint (gnomAD): Loss-of-function variants: 16 observed, 16.52 expected, observed/expected ratio (o/e) 0.97, 90% interval 0.65 to 1.47. The upper end of that interval is the gene's LOEUF score, 1.47, which puts it in group 6 of 6, group 1 being the genes least tolerant of losing a copy. Missense variants: 400 observed, 407.77 expected, observed/expected ratio (o/e) 0.98, 90% interval 0.9 to 1.07. Synonymous variants: 180 observed, 172.79 expected, observed/expected ratio (o/e) 1.04, 90% interval 0.92 to 1.18.
Homologues: Orthologues: chimpanzee LRRC52 (99% identical), macaque LRRC52 (95% identical), guinea pig LRRC52 (82% identical), pig LRRC52 (82% identical), rabbit LRRC52 (81% identical), dog LRRC52 (80% identical), rat Lrrc52 (76% identical), mouse Lrrc52 (74% identical), zebrafish lrrc52 (39% identical), tropical clawed frog lrrc52 (37% identical), Drosophila melanogaster kek3 (22% identical), Drosophila melanogaster Con (20% identical), and 2 more. Paralogues in human: LRIG1 (26% identical), LRIG3 (25% identical), TRIL (24% identical), LRIG2 (23% identical), LGR4 (22% identical), CPN2 (22% identical), LRRC24 (22% identical), LGR5 (22% identical), LGR6 (21% identical), ELFN2 (19% identical), LRIT1 (19% identical), LRRTM2 (19% identical), and 10 more.
Diseases named in the same sentence as LRRC52 in open-access papers:
LRRC52 is named in the same sentence as 2 diseases in open-access papers, as found by Europe PMC text mining. Sharing a sentence is not in itself a finding about the gene and the disease. The quoted sentences say what the papers report.
atherosclerosis (3 papers, 2022 to 2025). A disease characterized by the build-up of fatty material and calcium deposition in the arterial wall resulting in partial or complete occlusion of the arterial lumen. "In a sample of African-Americans, DNA methylation of AHRR, GFI1, and LRRC52 were associated with atherosclerosis after adjusting for cardiovascular diseases risk factors." (PMID 38031118, 2023). "After adjusting for CVD risk factors, four CpGs (cg05575921(AHRR), cg09935388 (GFI1), cg21161138 (AHRR), and cg18168448 (LRRC52)) were associated with multi-site atherosclerosis (FDR < 0.1)." (PMID 35039093, 2022).
LRRC52 also shares sentences with these, for which no sentence is quoted: Hypertension (1 paper).